YAP1 (Yes1 associated transcriptional regulator)
Diseases named in the same sentence as YAP1 in open-access papers (continued):
Sharing a sentence is not in itself a finding about the gene and the disease.
pulmonary fibrosis (continued). "We provide evidence that in response to bleomycin-induced pulmonary fibrosis, increased Taz through inactivation of Yap1, Stk3/4, or Nf2 is vital for AT1 cell differentiation and reduction of fibrosis." (PMID 37166104, 2023). "Inactivation of Wwtr1 alone or in combination with Yap1 caused a drastic decrease in AT2 to AT1 cell differentiation, increased pulmonary fibrosis, and increased mortality in the latter (data not shown)." (PMID 37166104, 2023). "We have also shown a role for SPHK1/S1P signaling in TGF-β-induced YAP1 activation and mitochondrial ROS generation, resulting in fibroblast activation, a critical driver of pulmonary fibrosis." (PMID 36498853, 2022). "Other transcription factors and co-factors (e.g., TFII-I, GATA2, YAP1) that sense mechanical forces interact with Twist1, control angiogenesis, and contribute to age-related lung diseases (e.g., pulmonary fibrosis, pulmonary hypertension)." (PMID 33764901, 2021). "Melatonin attenuates lung fibrosis by inhibiting the expression and activation of YAP1 by binding to MT1 and MT2 Melatonin Receptors." (PMID 34445329, 2021). "In the present study, we found that lncRNA PFAR participates in pulmonary fibrosis by binding to miR-15a and regulating the expression of its downstream target YAP1." (PMID 31273058, 2019). "In our previous study, we found that miR-15a participates in the pulmonary fibrosis process by regulating YAP1-Twist axis." (PMID 31273058, 2019). "Other mechanosensitive transcription factors and co-activators (e.g., TFII-I, GATA2, Twist1, YAP1) also control angiogenesis, and contribute to lung diseases (e.g., pulmonary fibrosis, pulmonary hypertension)." (PMID 30612120, 2019). "The researchers suggest that enhancing YAP1 activity in lung cells could be a potential treatment for lung fibrosis." (PMID 38945958, 2024). "First, we aimed to explore the expression of YAP1 during pulmonary fibrosis." (PMID 38945958, 2024). "Hence, further research is needed to elucidate the precise role of YAP1 in AT2 cells through which BLM-induced pulmonary fibrosis was inhibited in our study." (PMID 38945958, 2024). "This study investigates the role of a protein, YAP1, in lung fibrosis." (PMID 38945958, 2024). "In conclusion, this study demonstrated that YAP1 alleviates lung injury and pulmonary fibrosis by regulating Prdx3 expression to improve mitochondrial dysfunction and block senescence in AT2 cells, revealing a potential novel therapeutic strategy for pulmonary fibrosis." (PMID 38945958, 2024). "Collectively, these results indicated that the expression of YAP1 in AT2 cells is decreased during pulmonary fibrosis, which may contribute to the progression of IPF." (PMID 38945958, 2024). "MiR-15a targets YAP1 to inhibit pulmonary fibrosis both in vivo and in vitro experiments." (PMID 31273058, 2019). "Notably, in our previous studies, we illustrated that YAP1 contribute to the process of lung fibrosis." (PMID 29642520, 2018). "YAP1 was significantly up-regulated in BLM-induced lung fibrosis, which was abrogated by melatonin." (PMID 29642520, 2018). "Therefore, we assume that melatonin alleviates pulmonary fibrosis by inhibiting the functional role of YAP1 via binding to melatonin receptors." (PMID 29642520, 2018). "Taken together, our results suggest that melatonin prevents lung fibrosis by inhibiting YAP1 and indicate that melatonin replacement could be a novel strategy for the treatment of lung fibrosis." (PMID 29642520, 2018). "Moreover, melatonin alleviated lung fibrosis in vivo and in vitro by binding to its receptor, and this anti-fibrotic effect was mitigated by up-regulation and functional activation of YAP1." (PMID 29642520, 2018). "The present work revealed that melatonin alleviates lung fibrosis through YAP1 regulation." (PMID 29642520, 2018).
pulmonary fibrosis (continued). "Therefore, we hypothesized that NPNT might act on ITGA3 to regulate the intracellular Hippo/YAP1 axis, influence the aging of alveolar epithelial cells, and subsequently impact the progression of pulmonary fibrosis." (PMID 40444575, 2025). "Hence, we elucidated that targeting the YAP1/TEAD1-Prdx3 axis may be an effective therapeutic strategy for pulmonary fibrosis." (PMID 38945958, 2024). "Thus, we hypothesized that YAP1 prevents pulmonary fibrosis by inhibiting the senescence of AT2 cells and promoting the regeneration of pulmonary alveoli." (PMID 38945958, 2024). "In contrast, overexpression of YAP1 in AT2 cells promoted alveolar regeneration, mitigated pulmonary fibrosis, and improved lung function." (PMID 38945958, 2024). "Overall, we propose the role of the YAP1/TEAD1-Prdx3 axis in regulating AT2 cell senescence and pulmonary fibrosis, revealing a novel strategy for the treatment of pulmonary fibrosis." (PMID 38945958, 2024). "Overall, our study revealed that the YAP1/TEAD1-Prdx3 axis inhibits lung senescence, promotes cell survival and lung repair, and alleviates pulmonary fibrosis." (PMID 38945958, 2024). "These trends indicated that circELP2 sponging of miR‐630 targeted YAP1 and TAZ to promote pulmonary fibrosis." (PMID 38159063, 2024). "Overall, our research demonstrated that YAP1 attenuated the chronic injury-induced senescence of AT2 cells and inhibited pulmonary fibrosis." (PMID 38945958, 2024). "Pulmonary function tests and micro-CT analysis demonstrated that Prdx3 silencing increased pulmonary fibrosis in BLM-treated YAP1-cKI mice, indicating that YAP1 inhibited BLM-induced pulmonary fibrosis through Prdx3 in vivo." (PMID 38945958, 2024). "A study of MEG3 expression in idiopathic pulmonary fibrosis using scRNA-seq demonstrated that MEG3 regulates the differentiation of bronchial cells through diverse mechanisms, including through YAP1, NOTCH, and SOX2 signaling." (PMID 36231143, 2022). "Further studies are essential to determine potential interactions between SPHK1/S1P/YAP1 and NOX4 in the modulation of TGF-β mediated mtROS and pulmonary fibrosis." (PMID 32192225, 2020). "Silencing of Prdx3 abolished the beneficial effects of YAP1, indicating the vital role of the YAP1/TEAD1-Prdx3 axis in inhibiting cellular senescence and maintaining cell survival, whereas overexpression of Prdx3 in AT2 cells alleviated pulmonary fibrosis." (PMID 38945958, 2024). "Interestingly, the inactivation of only Yap1 in AT2 stem cells promoted alveolar epithelial regeneration and reduced pulmonary fibrosis." (PMID 37166104, 2023). "However, the inactivation of Yap1 by itself in AT2 cells resulted in increased AT2 to AT1 cell differentiation and decreased pulmonary fibrosis based on hydroxyproline content and significantly less Col1a1 and Col3a1 RNA expression." (PMID 37166104, 2023). "Knockdown of YAP1 reduced ECM deposition and attenuated lung fibrosis." (PMID 35805148, 2022). "In the lung, YAP1 activation in alveolar epithelial stem cells and ECs promotes post-PNX lung growth, while deregulation of YAP1 contributes to chronic obstructive pulmonary disease and pulmonary fibrosis." (PMID 35252132, 2022). "YAP1/TAZ activated or inhibited genes expression in the mitochondrial quality control pathway by binding to the promoter regions of mTOR, Raptor and mLST8, thereafter accelerating the fibroblast–myofibroblast differentiation and extracellular matrix deposition to promote pulmonary fibrosis." (PMID 38159063, 2024).
small cell lung carcinoma (20 papers, 2013 to 2025). Small cell lung cancer (SCLC) is a highly aggressive malignant neoplasm, accounting for 10-15% of lung cancer cases, characterized byrapid growth, and early metastasis. "Upregulation of nuclear YAP1 is associated with poor survival, and YAP1 enhances the resistance to drugs through CD74 signaling in small cell lung cancer." (PMID 41184230, 2025). "For example, non-YAP1-driven small cell lung cancer (SCLC) and brain tumors with IDH1/2 mutations represent cancer subsets that are suitable for HDAC-targeted therapy." (PMID 38225241, 2024). "Conversely and interestingly, in a specific subset of small cell lung cancer cell lines and patients, the loss of YAP1 has been shown to be associated with an increase of neuroendocrine markers and a poorer prognosis similar to what has been observed in haematologic malignancies." (PMID 29734788, 2018). "We also included 10 SNPs in the gene YAP1, in light of its association with response to platinum-based chemotherapy in small-cell lung cancer patients, to test whether this finding would replicate in our study." (PMID 26840454, 2016). "Intriguingly, a recent research identified a YAP1 variant, rs1820453, was associated with survival of small-cell lung cancer patients and the variant A>C change created a transcriptional factor binding site which then resulted in the down regulation of YAP1 expression." (PMID 24223879, 2013). "In small cell lung carcinoma, transcription factors such as NEUROD1, achaete-scute family bHLH transcription factor 1 (ASCL1), POU class 2 homeobox 3 (POU2F3), and Yes1-associated transcriptional regulator (YAP1) are used for sub-classification." (PMID 39937015, 2025). "Our previous research found that YAP1 may have a role in multidrug resistance (MDR) in small cell lung cancer (SCLC)." (PMID 31692299, 2020). "We also wondered about the distribution of TRIT1 gene amplification according to the small-cell lung cancer molecular subtypes ASCL1, NEUROD1, POU2F3, and YAP1." (PMID 33919717, 2021). "Small cell lung cancer (SCLC) has recently been characterized as heterogeneous tumors due to consensus nomenclature for distinct molecular subtypes on the basis of differential expression of four transcription markers (ASCL1, NEUROD1, POU2F3, and YAP1)." (PMID 35311069, 2022). "Small-cell lung cancer (SCLC) is an aggressive malignant cancer that is classified into four subtypes based on the expression of the following key transcription and co-transcription factors: ASCL1, NEUROD1, YAP1, and POU2F3." (PMID 33202998, 2020).
liver fibrosis (18 papers, 2016 to 2025). "For example, YAP-1 has been implicated in developing cardiovascular disease, liver fibrosis, and other conditions." (PMID 37476371, 2023). "Further, pharmacological inhibition of P21-activated kinase (PAK) or the mechanosensitive factor Yes-associated protein-1 (YAP-1), two mediators of β1-integrin-controlled profibrotic signaling, reduced liver fibrosis induced by CCl4 and bile duct ligation." (PMID 31771248, 2019). "Rationale: Hedgehog (Hh) pathway plays an essential role in liver fibrosis by promoting the proliferation of hepatic stellate cells (HSCs) by enhancing their metabolism via yes-associated protein 1 (YAP1)." (PMID 31695785, 2019). "In the context of fibrosis and increased organ stiffness, studies in development, liver fibrosis and regeneration all support mechanisms involving the mechanosenstive factor Yes associated protein-1 (YAP-1) as important in the regulation of SOX922–24." (PMID 30559459, 2018). "Increase in YAP1 nuclear translocation can inhibit ferroptosis of HSCs in carbon tetrachloride (CCl4)-induced mouse liver fibrosis model." (PMID 39917623, 2025). "YAP1 activation was found to suppress the infiltration of macrophages and neutrophils and reduce the activation of HSCs and liver fibrosis." (PMID 39917623, 2025). "Pharmacological inhibition of either PAK or YAP1 markedly ameliorates experimental liver fibrosis, with PAK inhibitors producing the most rapid suppression of the myofibroblast phenotype and limiting postinjury scar expansion." (PMID 41377763, 2025). "YAP‐1 acts as the core mediator of fibrotic integrin β‐1 signaling, playing a crucial role in liver fibrosis." (PMID 40066231, 2025). "Myeloid-specific Yap1 knockout mice using LysMCre mice attenuated liver fibrosis after chronic CCl4 injury as the amount of α-SMA, collagen I, and the hydroxyproline content were impaired in Yap1 knockout mice." (PMID 35805148, 2022). "In this context, pharmacological inhibition of either pathway in vivo attenuates liver fibrosis and suggests a synergistic effect in the combined inhibition of integrins and the mechanosensor YAP1." (PMID 32466585, 2020). "Taken together, our data support a model whereby injury induces SOX9 downstream of YAP1 in HSCs to promote liver fibrosis." (PMID 29109128, 2017). "Here the authors identify an axis of integrin beta-1 expression and Yap-1 and Pak protein signalling that can be interfered with to inhibit myofibroblast function and liver fibrosis in vivo." (PMID 27535340, 2016). "Notably, we found that VDR activation can induce YAP1 expression at the transcriptional level in liver tissue and HSC line and increased YAP1 further exerts its inhibitory effect on NLRP3 expression to alleviate cholestatic liver fibrosis and injury." (PMID 32296329, 2020). "YAP1 is also a core mediator of integrin β1 signaling in liver fibrosis." (PMID 32466585, 2020). "To explore whether blocking YAP-1 function might ameliorate liver fibrosis, we administered VP to mice in two different models of liver fibrosis." (PMID 27535340, 2016). "Previously, our group showed that the interaction of TSG-6 with CD44 activated β-catenin/YAP-1 signaling and reprogrammed activated HSCs into stem-like cells, mitigating HSC activation and liver fibrosis in mice with chronic liver damage from CCl4." (PMID 38790021, 2024). "To date, a variety of intracellular signaling pathways including acid ceramidase, fibroblast growth factor 18 and Hedgehog signaling pathways have been shown to act as a modulator of YAP1 activity, thereby altering HSC activation and liver fibrosis." (PMID 36091042, 2022). "Low SMAD7/high YAP1 levels were confirmed in both HCC and rat models with advanced liver fibrosis and cirrhosis." (PMID 33763375, 2021). "Inhibition of YAP1 in CCl4 and BDL-induced liver fibrosis by injection of specific YAP1-related inhibitor Verteporfin resulted in decreased expression of SOX9 in HSCs." (PMID 34062960, 2021).
liver fibrosis (continued). "Taken together, these data demonstrate integrin beta-1 upstream of YAP-1 and PAK protein signalling in HSCs in vitro; the importance of all three to the pro-fibrotic phenotype of HSCs in vitro; and that inhibiting YAP-1 and PAK protein function in vivo ameliorates liver fibrosis." (PMID 27535340, 2016). "In summary, these data report new mechanisms for liver fibrosis involving the group 1 PAK proteins and YAP-1 as important effectors of integrin-dependent signalling in hepatic myofibroblasts and highlight PAK inhibitors as potential new agents with which to target liver fibrosis in patients." (PMID 27535340, 2016). "Although PAK proteins and YAP-1 have been detected in HSCs25, 26, PAK, YAP-1 and MYL9 have not previously been reported in integrin beta-1 signalling or collectively as regulators of HSC function/liver fibrosis and therefore we set about investigating these factors in greater detail." (PMID 27535340, 2016).
papillary thyroid carcinoma (17 papers, 2017 to 2025). "Recently, S100A1, a calcium-binding protein from the S100 family, was suggested to promote YAP1 activity in human papillary thyroid carcinoma cells in vitro and in vivo." (PMID 39397390, 2024). "YAP1 was highly expressed in papillary thyroid carcinoma cases and its expression was significantly related to high-risk clinicopathological features of the patients." (PMID 37383164, 2023). "miR-506-3p downregulates YAP1 expression at the mRNA and protein levels, suppressing papillary thyroid cancer cell proliferation." (PMID 36470227, 2023). "In summary, our findings demonstrated that SNHG15 serves as a competitively endogenous RNA (ceRNA) to regulate YAP1-Hippo signaling pathway by sponging miR-200a-3p in papillary thyroid carcinoma." (PMID 30237435, 2018). "Here, we investigated the involvement of YAP1 in papillary thyroid carcinoma (PTC) by assessing YAP1 mRNA and protein levels in PTC tissues and matched normal thyroid epithelial tissues from 50 patients." (PMID 28036290, 2017). "YAP1 expression was observed in 70% of papillary thyroid carcinoma cases." (PMID 37383164, 2023). "Moreover, SNHG15 was confirmed to regulate YAP1-Hippo signaling pathway via sequestering miR-200a-3p in papillary thyroid carcinoma." (PMID 35101035, 2022). "Additionally, SNHG15 has been reported to act as a ceRNA to modulate the miR-200a-3p/YAP1-Hippo axis in papillary thyroid carcinoma." (PMID 33243205, 2020). "Finally, results of rescue assays validated the function of SNHG15-miR-200a-3p-YAP1 axis in papillary thyroid carcinoma." (PMID 30237435, 2018).